TNF (tumor necrosis factor)
Diseases named in the same sentence as TNF in open-access papers (continued):
Sharing a sentence is not in itself a finding about the gene and the disease.
COVID-19 (continued). "Additionally, there were higher correlations between IL-2 and IL-4, TNF-α and IL-2, TNF-α and IL-4, TNF-α and IFN-γ, and CD16+CD56+NK cells and various subsets of T cells in COVID-19 patients." (PMID 34712741, 2021). "In COVID-19 related cytokine storm syndrome (COVID-CSS), different inflammatory cytokines such as Interleukin-1 (IL-1), Interleukin-10 (IL-10), and tumor necrosis factor (TNF)-α are elevated about 2-100 fold above normative values." (PMID 35155571, 2021). "Control of inflammation (↓IL-8, TNF-α, ↑TGF-β) inAlzheimer disease.↓Severity of COVID-19." (PMID 34135894, 2021). "Our meta-analysis revealed significantly lower levels of immune cells (CD3+ T, CD4+ T, CD8+ T, B and NK cells), higher levels of cytokines (TNF-α, IL-5, IL-6 and IL-10) and higher levels of chemokines (MCP-1, IP-10 and eotaxin) in severe cases in comparison to mild cases of COVID-19." (PMID 34344353, 2021). "In order to investigate the contribution of innate immune cells to the production of the most prominent cytokines expressed during COVID-19, we analyzed the production of pro-inflammatory IFN-α, TNF-α, and IL-6 by in vitro differentiated innate immune cells upon SARS-CoV-2 infection." (PMID 34122407, 2021). "Biomarkers indicating rapid deterioration in COVID-19 patients are mostly represented by troponin I (TnI), CRP, erythrocyte sedimentation rate (ESR), D-dimer, progressive deterioration of lymphocyte counts and elevated inflammatory markers (IL-6, TNF-α)." (PMID 33916917, 2021). "Case reports describe continuing anti-TNF agents in patients with COVID-19, but not many patients were started on infliximab for UC within the first 14 days of the infection." (PMID 34981697, 2021). "TNF-α, IFN-γ, IL-6, IL-8, IL-4, and IL-10 were dramatically elevated in COVID-19 patients." (PMID 34646834, 2021). "The signaling cascade mediated by TNF-α and IFN-γ through the JAK/STAT1/IRF1 axis activates nitric oxide production amplifying the cytokine storm and cell death cycles, which mirror tissue damage and CRS observed in severe COVID-19 cases." (PMID 34737743, 2021). "Adverse events/severe adverse events, COVID-19 symptoms, SARS-Cov-2 virus test, blood SARS-Cov-2 IgM and IgG antibodies tests, blood cytokine and inflammatory (CRP, IL_6, IL-10, TNFα) tests and disease severity evaluation for 6 months after the last dose of AdMSC infusion for the SG and CG." (PMID 33815867, 2021). "Active AOSD patients also had significantly higher levels of IL-6 and TNF-α than non-severe COVID-19 patients." (PMID 34367188, 2021). "In the international registry database of COVID-19 in patients with IBD (SECURE-IBD), corticosteroids but not antitumor necrosis factor (anti-TNF) were associated with adverse outcomes of the COVID-19 infection (odds ratio (OR): 6.9; 95% CI: 2.3–20.5)." (PMID 34858891, 2021). "It is not surprising that anti-TNF-α drugs (adalimumab (A), certolizumab pegol (C), etanercept (E), golimumab (G), and infliximab (I)) are considered anti-COVID-19 treatments." (PMID 34063739, 2021). "TNF and IFN-γ, which are present at high concentrations in plasma of COVID-19 patients, may aggravate lymphopenia through direct killing of lymphocytes." (PMID 34201847, 2021). "COVID-19 patients without CHRFAM7A expression also showed increased TNF pathway expression in whole blood." (PMID 34088975, 2021). "Although some COVID-19 cases have very high serum concentration of IL-17, IL-1β and TNF-α, the average levels of these cytokines did not change dramatically compared to normal values." (PMID 33995382, 2021). "OE biopsy of COVID-19 patients showed significant increase in tumor necrosis factor alpha (TNF-α) but not IL-1β, as compared to levels in uninfected controls." (PMID 34835030, 2021).
COVID-19 (continued). "In ex vivo cell culture experiments, it was determined that the peripheral pDCs from COVID-19 patients were functionally impaired in IFN-α and TNF-α production in response to a synthetic mixture of viral TLR ligands, in comparison to those from healthy individuals." (PMID 33912590, 2021). "In addition, COVID-19 patients with severe disease have been shown to suffer from a rapid and excessive production of harmful pro-inflammatory cytokines (IL6, IL1-β, and TNF-α), or “cytokine storm”, triggered by the innate immune response against the virus." (PMID 34031383, 2021). "Modeling COVID-19 progression through DBNs by cytokines’ measurements over time identified notable dependencies among clinical and biological markers, where most of them are biomarkers of inflammation, including the IL-8, IL-6, CRP, LDH, and TNF." (PMID 35054223, 2021). "In agreement with other studies, we found that inflammatory cytokines are elevated in hospitalized COVID-19 patients compared with HC [median (IQR), all units picograms per milliliter: IL-6 4.65 (3.32–9.16) vs 0.69 (0.55–0.89), p < 0.001; TNFα 4.49 (1.87–8.03) vs 0.04 (0.04–0.84), p < 0.001]." (PMID 34792686, 2021). "In patients with severe, but not mild, COVID-19, we detected the putative interaction between TNF on monocytes and different members of the TNF receptor superfamily (i.e., FAS and TNFɑR1) expressed by mature and immature neutrophils." (PMID 34548411, 2021). "The SARS-CoV-2 S protein promotes NLRP3 inflammasome activation and IL-1β secretion in COVID-19 patient-derived macrophages, and stimulation of the S protein upregulates both IL-1β and TNF-α; however, TNF-α is secreted in an NLRP3 inflammasome-independent manner." (PMID 34360684, 2021). "Antigen-specific CD4+ T cells expressing memory markers as well as IL-2, IFN-γ, TNF-α, and CD154 were markedly increased in COVID-19–recovered individuals compared with healthy donors, but the relative frequency of these cells decreased at the 6.1-mo time point (clusters 2, 3, 4, and 6)." (PMID 33533915, 2021). "Moreover, in vitro, higher levels of IL-6, TNF-α and IL1-β were released from monocytes derived from COVID-19 patients compared to H1N1 2009 patients." (PMID 34728719, 2021). "ADAM17 is responsible for delivering the soluble forms of TNF, TNFR1, and TNFR2; we hypothesized COVID-19 patients had increased ADAM17, explaining why TNFRs levels increased." (PMID 34445140, 2021). "Several proinflammatory cytokines, such as tumor necrosis factor-α (TNF-α), interleukin (IL) 1β and chemotactic cytokines (e.g., IL-8 and macrophage chemoattractant protein-1 (MCP-1)) are upregulated during COVID-19, leading to a sustained increase in IL-6 levels." (PMID 34830648, 2021). "Other authors pointed out that the sum of IL-10 and TNF-α levels allowed to distinguish MISC from severe COVID-19 presentations, but not between severe and mild MIS-C." (PMID 34778310, 2021). "In COVID-19, increase of interleukins (IL-7, IL-2), inducible protein (IP)-10, granulocyte-colony stimulating factor, monocyte chemoattractant protein (MCP)-1 and tumor necrosis factor (TNF)-α are indicators of cytokine storm." (PMID 34833873, 2021). "Thus, this study aims to evaluate TNF/TNFR molecule levels in mildly, severely, and critically ill patients suffering from COVID-19 to provide evidence about their behavior during different stages of severity." (PMID 34445140, 2021). "COVID-19 (+) patients requiring intensive care unit (ICU) admission have higher TNF-α levels when compared to the patients who do not require treatment on ICU." (PMID 34575258, 2021). "Our data demonstrated strong enrichment of CCL2/19/20, CXCL10, GM-CSF, IL-6/8/15, S100A9, SCGF, TNF and TREM-1 in COVID-19, which could potentially play a critical role on the pathogenesis of the disease." (PMID 34238349, 2021). "Huang reported that ICU patients with COVID-19 had higher plasma levels of TNF-α than non-ICU patients." (PMID 34335579, 2021).
COVID-19 (continued). "In COVID-19, the immune response is characterized by high plasma levels of interleukins (IL-6, IL-2), interferons (IFN-y,) chemokines (CXCL10, CCL2, CCL3), growth factors (granulocyte colony stimulating factor) and tumor necrosis factor (TNFα)." (PMID 33557908, 2021). "Consistently, another study found that the levels of tumor necrosis factor-α (TNF-α) and IFN-γ in CD4+ T cells of severe COVID-19 patients were lower than those of mild patients, while the levels of granzyme B and perforin in CD8+ T cells of severe patients were higher than those of mild patients." (PMID 33987176, 2021). "Furthermore, we examined mRNA expression of cytokines (IL-6, TNF-α, and CXCL10) which are known to be upregulated in COVID-19 patients." (PMID 34815389, 2021). "In this study, we focused on TNFα, IL-1β, and IL-6 as known pro-inflammatory markers of acute inflammatory response, along with CXCL8/IL-8 because of its potent role in the recruitment and activation of neutrophils, commonly elevated in patients with COVID-19." (PMID 34360706, 2021). "HuR may also be involved in the pathogenesis of COVID-19 by its ability to increase inflammation, as SARS-CoV-2 infection induces TNF-α, IL-6, and CC-chemokine ligand 2 (CCL2)." (PMID 35011584, 2021). "Specifically, IFN, TNF and NF-kB pathways, cytokine SPP1, GRN, the receptor tyrosine kinase AXL [TE85], NLR and RIG-I signaling are strongly altered by SARS-CoV-2 [TE76], contributing to severe forms of COVID-19." (PMID 34876157, 2021). "CMV also stimulates the production and release of the same chemokines and cytokines that were found to be elevated in COVID-19 patients and to be involved in the cytokine storm—such as MCP-1, MIP-1α, IP10, IL-1β, IL-2, IL-8, IL-10, IL-17, G-CSF, GM-CSF, and TNF-α." (PMID 34830421, 2021). "Even knowing that TNF-α is a decisive factor in the emergence and progression of the life-threatening cytokine storm in COVID-19 patients, the specific role of TNF-α in SARS-CoV-2 infections is not yet clarified." (PMID 33445810, 2021). "COVID-19 patients are also reported to show CD4+ lymphopenia; CD8+ lymphopenia; and higher levels of cytokines such as interleukin (IL)-6, IL-10, and tumor necrosis factor alpha (TNF-α)." (PMID 34360684, 2021). "Our data indicate that MAIT cells are highly activated in patients with COVID-19, irrespective of the course of disease, and express high levels of proinflammatory cytokines such as IL-17A and TNFα ex vivo." (PMID 33546489, 2021). "In contrast, the serum levels of IL-4, IL-6, IL-10, interferon-γ, and TNF-α were lowest in infected HD patients compared to non-infected HD patients or COVID-19-infected patients with normal renal function." (PMID 33466527, 2021). "Consistent with systemic inflammation, COVID-19-derived PBMCs but not HC cells spontaneously released IL-1β, and also IL-6 and TNF-α ex vivo (respectively)." (PMID 35095880, 2021). "In monocytes from severely affected COVID-19, IFN-1 response, and TNF/IL-1β-driven inflammation co-existed and were absent in patients with milder COVID-19." (PMID 34940755, 2021). "The IL-2 levels in both the non-ICU and ICU COVID-19 patients were low (median level 0.29 pg/mL), almost within the normal ranges, whereas the levels of TNFα were slightly elevated in both the studied groups." (PMID 34071149, 2021). "Our synthesized results revealed significantly lower levels of immune cells in CD3+ T, CD4+ T, CD8+ T, B and NK cells, higher levels of cytokines (TNF-α, IL-5, IL-6 and IL-10) and higher levels of chemokines (MCP-1, IP-10 and eotaxin) in severe cases compared with mild cases of COVID-19." (PMID 34344353, 2021). "The cytokine profile of patients with severe COVID-19 is characterized by an increase of several cytokines, mainly (but not restricted to) IL-1β, IL-2, IL-6, IL-7, IL-8, and TNF-α." (PMID 33669218, 2021).
COVID-19 (continued). "The progress of COVID-19 from mild illness to severe form depends on the circulatory levels of inflammatory cytokines and chemokines such as IL-7, IL-8, IL-9, IL-10, GCSF, GMCSF, TNFα, and VEGFA." (PMID 34786427, 2021). "Recent published studies in adult populations have reported that elevated levels of inflammatory cytokines levels such as TNF-α, IL-1β, IL-6, IL-10, IL-17, IL-18, IFN-γ are seen in active COVID-19 individuals compared to seropositive individuals and healthy controls." (PMID 33813138, 2021). "Additionally, TNFα and MAPK promote the secretion of IL-6, contributing to the cytokine storm in COVID-19 patients." (PMID 34603282, 2021). "Collectively, based upon the findings of TNF-α upregulation in SARS-CoV2-infected iCMs, TNF-α may serve as a critical factor to potentiate SARS-CoV2 infection and hence worsen the manifestations of COVID-19." (PMID 34576032, 2021). "After controlling for important confounders, patients using anti-TNF therapy for the underlying rheumatic disease were found to have significantly less hospitalization need related to COVID-19, compared to those without anti-TNF inhibitor therapy." (PMID 34803441, 2021). "Recently, it was observed in a study that in normal patients, there was a lower level of classical inflammatory cytokines like G-CSF, CCL-20, IL-1β, IL-2, IL-6, IL-15, TNF-α, and TGF-β while at the same time, there was a higher plasma level of GM-CSF and CXCL-10 in COVID-19 patients." (PMID 34305892, 2021). "IFN, TNF-α, and IL-1β co-drive inflammatory responses in the monocytes of patients with severe COVID-19, but not in those of patients with mild COVID-19." (PMID 34746034, 2021). "As shown by the heatmap analysis, the association between the absence of CHFRAM7A expression and the increase in TNF signaling pathway was observed for patients with moderate and severe COVID-19 patients but not for those with critical disease." (PMID 34088975, 2021). "Serum TNF-α levels were similar between COVID-19 subjects upon ICU admission and non-ICU patients (7.18 ± 0.94 vs 5.73 ± 0.26 pg/ml, P=0.0725)." (PMID 33968010, 2021). "The possible increase of IL-2, IL-12, TNF-α, and interferon (IFN)-γ levels after mRNA COVID-19 vaccination might be the rationale for new onset psoriasis and flares after mRNA COVID-19 vaccine administration." (PMID 34945136, 2021). "Indeed, the plasma levels of interleukin-2 (IL2), interleukin-6 (IL-6), tumor necrosis factor α (TNFα), and C-reactive protein (CRP) are markedly elevated in COVID-19 patients." (PMID 34326911, 2021). "TNF-α and IFN-γ had lower level in COVID-19 patients compared with the CAP patients." (PMID 34150910, 2021). "Treatment with TNF-, IL-17-, and IL-6-inhibitors was not reported to be changed by the treating rheumatologists because of COVID-19 vaccination." (PMID 34498112, 2021). "To investigate the role of cytokines and chemokines in the inflammatory status of COVID-19 and MIS-C, we measured plasma levels of IL-1ß, IL-2, IL-4, IL-5, IL-6, IL-10, TNF-α, IL-17A, IFN-α, IFN-γ, CXCL10/IP-10, CXCL8/IL-8, CXCL9/MIG, CCL5/RANTES, and CCL2/MCP1." (PMID 33841438, 2021). "TNFα and GM-CSF were also more concentrated in COVID-19 patients compared to controls, but the differences were not statistically significant." (PMID 34248910, 2021). "Elevated production of inflammatory mediators at day 7 postinfection, a late time point, indicates that a profound immune response resulted from infection and aligns with increased levels of inflammatory mediators, including IL-1β, IFN-γ, TNF-α, and CXCL10, detected in COVID-19 patients." (PMID 33879586, 2021).
COVID-19 (continued). "Severely ill patients hospitalised with COVID-19 exhibit increased levels of Interleukin (IL)-1β, IL-2, IL-6, IL-7, IL-8, IL-10, IL-17, granulocyte colony stimulating factor (G-CSF), monocyte chemoattractant protein 1 (MCP-1) and tumor necrosis factor (TNF)." (PMID 34205262, 2021). "Similar effects may be observed in COVID-19 through infection of theendothelial cells of the BBB through largely overlapping inflammatory markers, notablyIL-6, tumour necrosis factor alpha(TNF-α) and reactive oxygen species." (PMID 34222864, 2021). "In addition, mRNA expression of the pro-inflammatory cytokines TNF and IL1B, which are implied in the progression of COVID-19, were strongly reduced." (PMID 33585804, 2021). "For most severe patients with COVID-19, the levels of pro-inflammatory cytokines soared in the serum, similar to that in SARS and MERS, including IL-6, IL-1β, IL-2, IL-8, IL-17, G-CSF, GM-CSF, IP10, MCP1, MIP1α, and TNF-α." (PMID 33178109, 2020). "In contrast, TLR4 may contribute to the cytokine release (e.g., TNF) induced by HMGB1 in immune cells, which is also related to COVID-19." (PMID 33313438, 2020). "COVID-19 patients were followed over time with serial ELISpot assays, and the mean number of IFN-ɣ– and TNF-α–producing cells remained suppressed and did not increase over the time course of disease (IFN-ɣ P = 0.54, TNF-α P = 0.42)." (PMID 32687484, 2020). "Indeed, tumor necrosis factor (TNF), a key cytokine driving COVID-19 pathogenesis, downregulates lung CFTR protein expression, providing a strong rationale that acquired CFTR dysfunction arises in the context of COVID-19 infection." (PMID 33250777, 2020). "Clinical studies show that the levels of IL-2, TNF-α, IFN-γ, IP-10, MCP-1and other pro-inflammatory cytokines are significantly increased in severe or critical patients with COVID-19, while SARS-CoV-2 infection also increases secretion of anti-inflammatory cytokines (IL4 and IL10)." (PMID 32665783, 2020). "This is in accordance with other pro-inflammatory cytokines that were reportedly increased in the peripheral blood of patients with COVID-19, such as the Th-17 inducing cytokine IL-6, IL-10, IL-2 and the Th1 signature cytokines interferon gamma (IFN)-γ and tumor necrosis factor (TNF)-α." (PMID 32512702, 2020). "In severe cases of SARS, MERS, and COVID-19, the secretion of a number of pro-inflammatory cytokines, including IL-6, IL-12, IFN-γ, and TNF-α, was increased compared to mild cases, suggesting that an overactive cytokine response plays a role in disease severity." (PMID 33374514, 2020). "Group 1 pediatric patients with COVID-19 who recovered without sequelae exhibited the lowest ADCP activity and had the lowest serum concentrations of IL-6 and TNF, cytokines associated with ARDS, and poor outcome in clinical studies." (PMID 32958614, 2020). "In the case of outpatients under immunosuppression with proven COVID-19 more than 50% of the respondents would refrain from administering intravenous high-dose steroids, cyclophosphamide, anti-CD20 antibodies as well as BAFF, CTLA‐4 and TNF-alpha blockades." (PMID 32809050, 2020). "Severe lung and systemic inflammation is believed to result from cytokine dysregulation; in patients with SARS elevated levels of cytokines such as TNF, CXCL10, IL-6, and IL-8 likely contributed to the poor outcome, strikingly similar to cytokine storm reported in severe COVID-19 patients." (PMID 33133083, 2020). "No conclusive evidence for or against the use of non-steroidal anti-inflammatory drugs (NSAIDs) in the treatment of COVID-19 patients is available, nor is there evidence indicating that TNFα blockade is harmful to patients in the context of COVID-19." (PMID 32256705, 2020). "Interestingly, TNF and IL1B, major genes in the inflammatory response, were identified as COVID-19-specific and commonly up-regulated genes, respectively." (PMID 32651212, 2020).